CDH1 (cadherin 1)
Diseases named in the same sentence as CDH1 in open-access papers (continued):
Sharing a sentence is not in itself a finding about the gene and the disease.
tumor (continued). "The mutation frequency and tumour mutational burden (TMB) of the two groups were calculated using the maftools package in R. The mutation frequencies of PIK3CA, CDH1, GATA3, and MAP3K1 were higher in the “Low-risk” group compared to those of the “Low-risk” group." (PMID 41221278, 2025). "We analyzed the expression of the epithelial cell marker gene CDH1 and the mesenchymal cell marker gene CDH2, finding that CDH1 expression decreased while CDH2 expression increased in malignant tumor epithelial cells as the tumor progressed from primary to metastatic stages." (PMID 41050411, 2025). "Furthermore, NDRG1 can mitigate Erastin-induced ferroptosis and promote tumor progression, with eight genes, including HSPA8 and CDH1, potentially being part of its underlying molecular mechanisms." (PMID 40386780, 2025). "Inhibiting histone deacetylases may also reverse chromatin compaction around the CDH1 locus, allowing re-expression of E-cadherin and potentially re-sensitizing tumor cells to adhesion-mediated death pathways." (PMID 40757085, 2025). "Notably, some genes (e.g., MET, HSPA6, ID1, MECOM, POU2AF1, SFRP4, CDH1) exhibited expression predominantly in tumor cells and a limited number of other cell types." (PMID 40954493, 2025). "In NSCLC, the downregulation or loss of CDH1 and upregulation of CDH2 is frequently observed and is associated with increased invasiveness and the ability of tumor cells to detach from the primary tumor site." (PMID 40860670, 2025). "Moreover, CDH1-mutant tumours displayed higher ERα activation scores and greater ERα positivity by immunohistochemistry." (PMID 40500450, 2025). "In HNSC, where high MSI frequently correlates with aggressive behavior and poor prognosis, elevated CDH1 expression may help preserve cellular integrity, potentially limiting the tumor’s invasive capacity." (PMID 41048343, 2025). "In addition to CDH1 deficiency, DGC, often accompanied by RHOA gene mutation and activation of the YAP downstream signaling pathway, promotes tumor survival." (PMID 38410129, 2024). "Promoter hypermethylation leading to decreased protein levels has also been documented in EAOC for several other tumor suppressor genes encoding Runt-related transcription factor 3 (RUNX3), E-cadherin (CDH1), the Ras-association domain family of gene 2 (RASSF2), and CDKN2A/p16." (PMID 39062866, 2024). "E-cadherin (CDH1) is a vital player in this process and considered to be a tumor suppressor." (PMID 39172098, 2024). "In this group, we also identified the germline variants in matched tumor specimens but not additional CDH1 somatic variants." (PMID 38652475, 2024). "Dysregulation of CDH1 leads to tumor proliferation, invasion, migration, and metastasis." (PMID 38826894, 2024). "However, for the ATC01 spheroids, the CDH2 to CDH1 ratio was relatively closer to the ones in the parental tumor in comparison to monolayer cultures." (PMID 38500204, 2024). "Previous study has shown that β-catenin may regulate the expression of CDH1 in ACP, which is the most critical gene for the occurrence and development of ACP; moreover, its decreased expression has been associated with tumour recurrence." (PMID 38594611, 2024). "Furthermore, we observed an upregulation of FAK in specific tumor types with gene mutations or aberrant protein expression, such as BRAF/KRAS mutations, CDH1 deletions, EGFR or HER2 overexpression, and mediated drug resistance processes." (PMID 38410129, 2024). "F. nucleatum interacts with CDH1 in colorectal cancer cells, promoting tumor progression." (PMID 38698370, 2024). "Besides, PKM2 in nucleus can reduce CDH1 gene encoding E-cadherin, and facilitating EMT and tumor cell invasion." (PMID 37815895, 2023).
tumor (continued). "In addition, administration of a FAK inhibitor promoted the anti-tumor effect of ROS1 inhibitors for both original and crizotinib-resistant CDH1-deficient cancer cells." (PMID 37324948, 2023). "Three pathogenic variants were identified: c.1320+1G>A in the CDH1 gene and c.27_28insCCCAGCCCCAGCTACCA (p.Ala9fs) of the VEGFA gene were found only in the tumor tissue, whereas c.G1874C (p.Cys625Ser) in the FANCA gene was found in both the tumor and normal tissue." (PMID 36833207, 2023). "In addition, we found that the patients with tumours with mutations in PIK3CA, BRAF, CDH1, and NRAS exhibit better survival outcomes than those without mutations in these genes." (PMID 37550388, 2023). "The screening results suggested that the loss of two members of the E-cadherin complex, CDH1 and CTNNA1, could be mediators of the BECN1-mediated tumour suppressor mechanism." (PMID 37686639, 2023). "In addition, we found that CDH1, CDH, and DESMOSOME ligand receptor pairs have strong associations inside tumor cells." (PMID 37213285, 2023). "Furthermore, 50% of CDH1 second hits in primary tumours were epigenetic modifications while a significantly greater proportion in metastases were LOH at 58.3%." (PMID 36869400, 2023). "CDH1 belongs to a family of transmembrane glycoproteins that mediate cell–cell adhesion and regulate cell growth, making them therapeutic targets for preventing tumor progression." (PMID 37728212, 2023). "Hypermethylation of CDH1 promotes stem cell-like properties of tumor cells." (PMID 36810560, 2023). "Similarly, the proportion of variants that were present on tumor testing only varied widely by gene, with the highest proportion found in RAD51C (100%, N = 2) and CDH1 (90%, N = 9) and the lowest proportion found in CHEK2 (0%, N = 0)." (PMID 35962742, 2023). "CDH1 is a tumor suppressor that inhibits multiple steps of metastatic cascade." (PMID 37620794, 2023). "In addition, 61/112 genes were upregulated in knockout mice for Fshr and for three other tumor suppressor genes (Pten, Cdh1 and Smad3) known to regulate follicular homeostasis in the mammalian ovary." (PMID 38203684, 2023). "In addition, the CDH1 mRNA upregulation occurs in the early stages of tumor development and the levels remain elevated as tumors progress to later stages across most carcinoma types." (PMID 37189027, 2023). "By increasing the expression of CDH1 (E-cadherin), calcitriol thereby promotes intercellular adhesion, inhibits the rolling of tumour cells and their adhesion to microvascular endothelial cells, i.e., the extravasation stage preceding metastasis, and blocks the CXCL12/CXCR4 chemokine axis." (PMID 37299554, 2023). "Additionally, CDH1 expression (epithelial marker) was observed in basal SCC25-derived tumours whereas mesenchymal SCC15 tumours were positive for PDPN (p-EMT marker)." (PMID 36949044, 2023). "SMAD5 was found to be a tumor suppressor candidate and CDH1 is a tumor suppressor, too." (PMID 36835463, 2023). "Hence, some modulators such as phenethyl isothiocyanate (PEITC) can destroy tumor cells by eliminating CSC-like properties by demethylating CDH1." (PMID 36810560, 2023). "LOXL2 participates in the repression of E-cadherin CDH1, a hallmark of the epithelial to mesenchymal transition (EMT) that is believed to amplify tumor aggressiveness, suggesting that it may play a role in tumor progression." (PMID 37056396, 2023). "E-cadherin encoded by CDH1 is an important epithelial cell adhesion protein and a tumor suppressor." (PMID 37986009, 2023). "Hence, CYSLTR1 and CYSLTR2 expression influenced tumor metastasis through the alteration of EMT marker expression (CDH1 and VIM)." (PMID 36834820, 2023).
tumor (continued). "The CDH1 gene, located on chromosome 16q22.1, is a well-known tumor suppressor gene." (PMID 36805828, 2023). "The genes with the most frequent SGMs associated with the three mutational processes are clearly enriched in core TSGs, including early oncogenic drivers such as APC, later drivers of tumor progression and metastasis such as CDH1, as well as less-characterized cancer genes such as EPHA2 and MGA." (PMID 37922356, 2023). "Obviously, the cadherin binding related genes including CTNNB1, CDH1, ITGA6, KRT18, and PROM1 were significantly associated with EpCAM, which also implied that EpCAM could play a role in tumor metastasis." (PMID 35517503, 2022). "Whilst the function of this non-coding mutation upstream of the TSS region of CTNNA1 is unknown, this may highlight an additional inactivation mechanism of CDH1 mediated through CTNNA1 in the EcadhetILC tumours." (PMID 35053458, 2022). "The human CDH1 gene is a 2.6 kb tumor suppressor gene located in chromosome 16q22.1." (PMID 36556253, 2022). "CDH1 (E-cadherin) was found to be downregulated in metastasis p-EMT tumor cells." (PMID 35742914, 2022). "Both play a role in tumorigenesis with Cdh1 being a tumor suppressor and Cdc20 an oncogene." (PMID 35832196, 2022). "Bioinformatics analysis of Oncomine, TIMER, TCGA, GEO and GEPIA databases in the present study revealed that CDH1 may function not only as a tumor suppressor but also as a pro-oncogene capable of accelerating the malignant progression of BC." (PMID 35784532, 2022). "These tumours were also CDH1 mutant, suggesting that the AID/APOBEC mutator phenotype is more likely to occur in tumours harbouring CDH1 mutations and may be a precursor to the acquisition of a CDH1 mutation." (PMID 35053458, 2022). "Circ-AKT3 may sponge miR-296-3p to promote CDH1 expression, thereby suppressing migration and invasion in vitro as well as tumor cell dissemination in vivo." (PMID 36114510, 2022). "ARID1A inactivation is associated with VIM activation and CDH1 suppression, which might serve as crucial molecules influencing COAD prognosis, accelerate tumour progression, and shorten patients' survival time, and promote metastases of COAD." (PMID 36420658, 2022). "Notably, we found p-EMT tumor cells (p-EMT sub-cluster) that highly expressed CDH1 (E-cadherin), keratin KRT14/16/17, TP63 (Tumor protein p63), and basement membrane ECM glycoprotein- Laminin family (LAMC2, LAMB3, LAMA3...)." (PMID 35742914, 2022). "We confirmed that after long term culture (at least 6 months), tumor cells derived from cells with high levels of Gata3 maintained their expression of Gata3 and E-Cad (encoded by Cdh1) (and data not shown)." (PMID 34976209, 2022). "The role of CDH1 as a tumor suppressor has previously been documented in cancer." (PMID 36142368, 2022). "CDH1 represses proto-oncogene Myc expression through the Wnt pathway, suggesting that the PPARα-CDH1 pathway may enhance tumor growth." (PMID 36507526, 2022). "Moreover, the LNEs showed increased inhibition of tumor growth of M subtype TNBC via restoration of CDH1/E-cadherin, and suppression of forkhead box M1 (FOXM1) expression." (PMID 35631368, 2022). "The accumulating β-catenin may then attach to CDH1 to create a complex, which may aid tumor cell invasion and metastasis." (PMID 36003502, 2022). "Similarly, in our study CDH1 gene expression downregulated in tumor tissues at all stages of the disease compared to control tissues." (PMID 36161592, 2022). "Moreover, these patients exhibited significantly lower overall survival, when compared with those harbouring tumours with a low ITGB1/high CDH1 molecular phenotype." (PMID 34486077, 2022). "Putatively, through CDH1-induction, dissemination from the primary tumor might be inhibited and migration towards distant sites is limited." (PMID 36359732, 2022).
tumor (continued). "Additionally, studies have been made on the expression of epithelial cadherin (E-cadherin) gene, CDH1, in a number of tissues and tumor cell lines with altered DG expression and/or glycosylation." (PMID 36494657, 2022). "Interestingly, two APC/C activators play opposing roles in tumorigenesis, with Cdh1 and Cdc20 identified as a tumour suppressor and an oncoprotein, respectively." (PMID 36499653, 2022). "Cell adhesion molecules such as ITGA3, CD47, MDK, ITGB1, CD55, and CDH1 show a trend of upregulation with pseudotime, indicating that cell-cell communications play an important role during the evolutionary process of tumor growth and progression." (PMID 35087839, 2021). "Eleven BC cell lines are annotated as “carcinoma”, “adenocarcinoma” or “ductal carcinoma”, with no detailed pathology report or molecular analysis of the corresponding clinical tumor specimens available, yet recent data show that they have key ILC genetic features, such as CDH1 mutation." (PMID 34771558, 2021). "Finally, the CDH1 gene is involved in mechanisms regulating cell–cell adhesions, mobility, and proliferation, and it is recognized as a tumour suppressor gene." (PMID 34835040, 2021). "Furthermore, we found that overexpression of BRCA1 in these cells induced expression of CDH1 (encoding E-cadherin) while inhibiting expression of FOSL1 (encoding FRA1) and VIM, consistent with our finding that deficiency of Brca1 induced EMT in tumor cells." (PMID 33478572, 2021). "Given our analysis of clinical specimens suggested a connection between MSI2 expression, E-cadherin/CDH1 expression, and tumor grade, particularly in tumor metastases, we analyzed whether MSI2 might directly regulate E-cadherin expression in CRC." (PMID 34237057, 2021). "Hypermethylation of tumor-related genes, such as cyclin-dependent kinase inhibitor 2A (CDKN2A), E-cadherin (CDH1), death-associated protein kinase (DAPK), phosphatase and tensin homolog (PTEN), and O6-methylguanine-DNA methyltransferase (MGMT), have been reported in HNC." (PMID 34206840, 2021). "Indeed, in a model of human ovarian cancer dormancy, anti-angiogenic genes are the genes most frequently affected, with enhanced TIMP3, TSP1, Ang1, and CDH1 expression as part of in dormant signature that is dampened upon tumor relapse and recurrence." (PMID 33738282, 2021). "Indeed, overlaying the tumor histology information (from the TCGA metadata) with UMAP classification indicated that ILC was over-represented in group 3, and CDH1 mutations, which are common in ILC tumors, were also found to be somewhat overrepresented." (PMID 34922480, 2021). "The CDH1 gene encodes E-cadherin which maintains cell–cell adhesion; therefore, lack of E-cadherin leads to decreased adhesion between cells and increased tumor invasiveness." (PMID 34679042, 2021). "As a consequence, inhibition of Cdk4/6 and/or activation of Cdh1 or pRb could provide a means to limit the proliferative capacity of tumor cells that have retained a functional G1 checkpoint." (PMID 33806417, 2021). "FGFR2b signaling may induce p38-dependent expression of CDH1 and its product E-cadherin, leading to tumor suppression." (PMID 34007277, 2021). "CDH1 was present in tumor cells of both groups under PBS and 5‐FU treatment conditions." (PMID 34042293, 2021). "Comparing tumor to parent cell, the cadherins CDH1 and CDH11 were different by −2 and 11.3-fold." (PMID 33808801, 2021). "In technical terms, it may be that qualitative analyses of CDH1 expression and semiquantitative E-cadherin immunohistochemistry cannot be performed in the same region of tumor." (PMID 35008529, 2021). "A putative relation between EGFR/KRAS mutation and the promoter methylation of CDH1, CDKN2Ap16, RASSF1A, TERT, and WT1 could influence tumor progression and therapy response." (PMID 32605217, 2020).
tumor (continued). "Furthermore, RT-qPCR and western blot analysis indicated that the expression levels of circ-ITCH and CDH1 were increased, whereas the miR-106a level was decreased in tumor tissues in circ-ITCH-overexpression group." (PMID 32714095, 2020). "Using functional assays, we found that inhibition of CDH11 expression in CAF-S1 fibroblasts significantly reduced CDH1/E-cadherin expression in tumor cells and CAF-S1-mediated pro-migratory effects on BC cell lines, thereby highlighting that CDH11 is a new key player in relapse in early luminal BC." (PMID 32665033, 2020). "miR-217-5p is overexpressed in tumor tissues and directly targets CDH1." (PMID 32987716, 2020). "Maintenance of CDH1/E-cadherin protein levels in tumor cells upon co-culture with CAF-S1 could explain the reduction of tumor cell migration we observed upon CDH11 silencing in CAF-S1." (PMID 32665033, 2020). "The decreased expression of CDH1 could reduce the ability of cell adhesion, dissociation and inhibit the invasion of tumor." (PMID 32714095, 2020). "Genes related to cancer pathways were downregulated upon atezolizumab treatment, including angiogenic factors for tumor vascularization (TNK1, AREG and KDR), proto-oncogenes (RET and MET) and tumor cell survival/migration/invasion (CDH1, RARA, WNK2, WNT4A, WNT9A, TGFB2, EGF, and LAMA3)." (PMID 32616706, 2020). "As we know, Cdh1 is generally accepted as a tumour suppressor, USP1 overexpression in HCC tissues may partially due to the dysregulation of Cdh1." (PMID 32951278, 2020). "By contrast, IDCs typically express CDH1 and hence grow as cohesive tumour nests." (PMID 33276802, 2020). "These TAC mRNA changes suggest interplay between non-silent CDH1 mutations and immune cell dysregulation in the tumour microenvironment." (PMID 31308365, 2019). "(iii) The inverse correlation found between the abundance of the NR2F1 mRNA and the transcripts for other signaling elements of the pathway under analysis in this work (VAV2, VAV3, and CDH1) in human tumor samples according to in silico coexpression matrix analyses." (PMID 30087437, 2019). "In addition to a high percentage of VIM-positive tumour cells, MSCCs had a low percentage of CDH1-positive cells and a high percentage of TWIST1-, ZEB1- and ZEB2-positive cells, characteristic of EMT." (PMID 31080552, 2019). "However, CDH1 was down‐expressed markedly in both MTX‐resistant tumour types as compared to their respective controls." (PMID 30592148, 2019). "In addition, we have identified IL1β and CDH1 expression by tumor cells as predictive markers for this interaction." (PMID 30993013, 2019). "The low expression of CDH1 in this bottom 10% of tumours cannot simply be attributed to high stromal cell contamination of DGCs, since tumours included in the TCGA analysis were restricted to those with a minimum tumour nuclei content of 60%." (PMID 30066183, 2019). "However, it remains elusive how Cdh1 restrains cancer progression and how tumor cells escape the inhibition of Cdh1." (PMID 31420536, 2019). "CDH1 is especially altered in hereditary diffuse GC (HDGC), where complete loss of protein expression often occurs due to a germline lesion and to a second hit, following Knudson’s theory of tumor suppressor gene inactivation." (PMID 31509966, 2019). "Nevertheless, we would like to note that the decrease in CDH1 expression was observed more commonly than the increase in miR-25 expression in NSCLC tumor tissues, suggesting that CDH1 is regulated by a mechanism in addition to miR-25 in NSCLC, which merits further investigation." (PMID 31208279, 2019).